ERBB2 (erb-b2 receptor tyrosine kinase 2)
Diseases named in the same sentence as ERBB2 in open-access papers (continued):
Sharing a sentence is not in itself a finding about the gene and the disease.
breast cancer (continued). "We next used the SK-BR-3 human breast cancer cell line with ErbB2 amplification to see whether Anks1a plays a role in EphA2-mediated ErbB2 signalling." (PMID 27619642, 2016). "Our report also shows that ERBB2 expression promotes invadopodia formation in breast cancer cells." (PMID 26899482, 2016). "An immunogenotypic signature of low complexity comprising MET relative copy number and Ki-67 expression generated by dual ISH and IHC may help predict pCR in ERBB2-positive breast cancer treated with neoadjuvant chemotherapy and trastuzumab." (PMID 27576528, 2016). "Moreover, overexpression of nucleolin is associated with enhanced disease progression and mortality rates in ErbB2-positive breast cancer patients." (PMID 27542246, 2016). "We hypothesize that alcohol may enhance the aggressiveness of breast cancer cells by stimulating the ErbB2/p38γ MAPK pathway and activating CSCs." (PMID 27416801, 2016). "We suggest that this approach could significantly potentiate the efficacy of existing ErbB2-targeted nano-therapeutic agents against breast cancer." (PMID 26859680, 2016). "Next, we determined whether Cav-1 expression is reduced in mammary tumors of genetically modified mice constitutively expressing activated c-neu (ErbB2) gene (FVB-MMTV-ErbB2)." (PMID 26543228, 2016). "In the present study, we investigated in human breast cancer cells whether a similar mechanism plays a role in the feedback regulation of the ErbB2/ErbB3 heterodimer, the most potent ErbB receptor dimer." (PMID 27531070, 2016). "Moreover, metformin prolongs the survival of murine ErbB2 transgenes and exhibits chemosensitizing properties in breast cancer cell line xenografts." (PMID 27164115, 2016). "One example of such a therapeutically targeted biomarker is the anti-ERBB2 monoclonal antibody, trastuzumab (Herceptin®, Genentech), developed using multiple, diverse ERBB2-overexpressing breast cancer cell lines, which is now a standard adjuvant therapy for ERBB2-positive breast cancer patients." (PMID 26955870, 2016). "We show here that alcohol exposure enhances the aggressiveness of breast cancer cells overexpressing ErbB2, which is evident by a significant increase in CSC population, mammosphere formation, migration/invasion as well as metastasis in MMTV-neu transgenic mice." (PMID 27416801, 2016). "EphA2/ErbB2 complex is important in promoting breast cancer but the mechanism by which these receptor tyrosine kinases are exported from the endoplasmic reticulum is unknown." (PMID 27619642, 2016). "It is reported that ErbB2 is a major driver of tumor growth in 20% of breast cancers." (PMID 27190992, 2016). "A similar pattern was observed in SKBR3 breast cancer cells, which endogenously express high levels of ErbB2: here, introduction of siRNA targeted against ErbB2 has significantly reduced ErbB2-nucleolin interaction, compared to untreated cells or cells treated with a non-specific control siRNA." (PMID 27542246, 2016). "Using clinical and transcriptional data from breast cancer patients obtained from the TCGA Research Network, we have performed bioinformatical analyses comparing disease onset and progression in either ErbB2-positive or ErbB2 and nucleolin-positive breast cancer patients." (PMID 27542246, 2016). "We previously showed that GLUT1 was the most abundantly expressed glucose transporter in cell lines derived from ERBB2/NEU-induced mouse mammary tumors and that shRNA-mediated reduction of GLUT1 in mouse mammary tumor cell lines decreased glucose uptake and proliferation without altering ATP levels." (PMID 27998284, 2016). "Furthermore, a notable improvement in P value was observed for lapatinib and ERBB2, a drug which is established as an effective treatment for ERBB2-positive breast cancer patients." (PMID 27654937, 2016).
breast cancer (continued). "Thus, our results suggest GroA should be further examined as a potential new treatment for ErbB2-positive breast cancer." (PMID 27542246, 2016). "The human epidermal growth factor receptor 2 (erbB2, HER2, or neu) is an oncogene involved in the proliferation, migration, and invasion of cancer cells; for example it has been found to be amplified in 18-20% of breast cancers." (PMID 27145373, 2016). "Additionally, and importantly, the finding of a homologous gene behavior and the recurrent occurrence of low erbB-2 expression levels in cat mammary tumors suggests that cat mammary neoplasias are a valuable model for erbB-2 negative human breast cancer." (PMID 29056725, 2016). "Characteristically, the (MMTV)-ErbB2 transgenes recapitulating human breast carcinogenesis carry the viral MMTV-LTR promoter in order to ectopically express the ErbB2 oncoprotein in mammary epithelium (ErbB2 is amplified in up to 30% human breast cancers)." (PMID 27164115, 2016). "As a proof-of-concept, we designed a bi-modular system that combines a Her2-targeting module (Her2 is a receptor tyrosine protein kinase, also called erbB-2, Her2/neu), which has been shown to be over-expressed in certain breast cancers), with a nucleoside-analog activating module." (PMID 27280468, 2016). "Maintaining the breast cancer cell lines in three-dimensional (3D) cell culture alters proliferation and morphology characteristics and may affect sensitivity to ErbB2 blockade." (PMID 27255951, 2016). "This study for the first time demonstrates ErbB2/p38γ MAPK/SAP97/DLG pathway may mediate alcohol-stimulated aggresiveness of breast cancer." (PMID 27416801, 2016). "We sought to determine whether more CSC population correlated to a high activity of ErbB2/p38γ MAPK in breast cancer cell lines." (PMID 27416801, 2016). "Indeed, HSP90 inhibitors, including GA, down-regulate ERBB2 very efficiently in several breast cancer cell lines." (PMID 27863425, 2016). "Clinically, breast cancer represents a heterogeneous disease that is mainly grouped based on its hormone receptor (estrogen receptor [ER] or progesterone receptor [PR] positivity) and amplification of the ERBB2 gene (hereafter referred to as HER2+)." (PMID 26835221, 2016). "Moreover, in breast cancer samples, TOM1L1 protein expression, assessed by immunohistochemistry (IHC), was significantly associated with both ER (P=0.027) and ERBB2 (P=0.001) expression." (PMID 26899482, 2016). "Breast cancer is a highly heterogeneous disease comprising estrogen receptor alpha (ERα)-positive and HER2/ERBB2/NEU-positive subtypes as well as triple-negative breast cancers (TNBCs) that do not express ERα, human epidermal growth factor 2 (HER2) or the progesterone receptor." (PMID 26781438, 2016). "The unexpected molecular similarity of cuSCC to specific subtypes of breast cancer may also highlight similar molecular vulnerabilities such as ERBB2/HER2." (PMID 27574101, 2016). "Whether ERBB2 fragment/s are formed in ERBB2 overexpressing breast cancer cells, the nature of the protease/s involved, the cell site of the cleavage, and the possible intracellular fate of this/these fragment/s, remain unclear." (PMID 27863425, 2016). "In other studies, ERBB2 had been reported as a significant biomarker of prognosis in other cancer types without EGFR-activating mutation such as breast cancer." (PMID 26824984, 2016). "Lapatinib, an EGFR/ErbB2 dual inhibitor, is used for advanced ErbB2-positive breast cancer cells." (PMID 26595522, 2016).
breast cancer (continued). "This exploratory analysis showed no significant prognostic impact of ERBB2 mutation on breast cancer-free interval and breast cancer specific survival (p = 0.82 and 0.35 respectively)." (PMID 27602491, 2016). "For example, it may be important to investigate whether hPEPD-G278D may synergize with trastuzumab to target ErbB2-overexpressing human breast cancer." (PMID 27286447, 2016). "ErbB2 is therefore an ideal target for breast cancer treatment." (PMID 26621843, 2016). "If ERBB2 is over-expressed, then the cell may get too many messages to proliferate and to survive, which may lead to breast cancer." (PMID 27112211, 2016). "Moreover, one of the four highly IRS4-positive samples in the random set of 27 human primary breast carcinomas was also one of the four ERBB2-positive samples." (PMID 27876799, 2016). "Interestingly, ezrin has been found in a molecular complex with CD44, Hsp90 and ErbB2 in mammary carcinoma cells." (PMID 27029001, 2016). "Thus, TOM1L1 is an important element of an ERBB2-driven proteolytic invasive programme and TOM1L1 amplification potentially enhances the metastatic progression of ERBB2-positive breast cancers." (PMID 26899482, 2016). "In samples from various cohorts of patients with breast cancer, ERRα mRNA positively correlates with the expression of the oncogene ERBB2 and inversely correlates to that of ERα and PR, which are considered as good prognostic markers for patients with breast cancer." (PMID 26074877, 2015). "However, the original pathology report also describes the primary breast cancer specimen as being ERBB2 positive (HER2 positive score 3+) according to IHC testing, which we also demonstrated by repeating ERBB2 protein-level staining of the primary specimen." (PMID 25970776, 2015). "Interestingly, paclitaxel is widely used in combinational breast cancer therapy including treatment of ERBB2-positive breast tumors." (PMID 25596742, 2015). "Currently, breast cancer can be subcategorized based on the status (+/−) of the hormone receptors oestrogen receptor (ER) and progesterone receptor (PR) and the Receptor tyrosine-protein kinase erbB-2 (ERBB2 or HER2)." (PMID 25721950, 2015). "The identification of LCNEC tumors with high ERBB2 expression levels suggests that a subset of these tumors might be sensitive to ERBB2 inhibitors, similar to ERBB2-positive gastric cancer and breast cancer." (PMID 25989941, 2015). "In addition, the cytotoxic effects of CUR were observed in breast cancer cells expressing either high or low levels of ErbB2/neu." (PMID 25918934, 2015). "HER2 (ErbB-2/Neu) is overexpressed in approximately 30% of primary human breast cancers (reviewed)." (PMID 25592291, 2015). "FN14 positivity was associated with ErbB2 expression in our series, consistent with reports that high FN14 expression levels were significantly correlated with several poor prognostic indicators, being higher particularly in ErbB2-positive breast cancer." (PMID 26497551, 2015). "ERBB2 is essential in initiating and driving breast cancer progression." (PMID 25853295, 2015). "We then examined ERBB2-induced breast cancer in mice at the transcriptomic level." (PMID 25853295, 2015). "To investigate whether ncRNA production in LTED cells is specific to the ESR1 locus, we examined the ERBB2 gene that plays a role in a subset of breast cancers." (PMID 25923108, 2015). "Focal somatic gene amplifications are also important targets for approved therapies, such as for trastuzumab, lapatinib, in ERBB2 (HER2) amplified breast cancer or gastroesophageal cancer, and for potential therapies in genes such as MET and CCNE1 in multiple cancers." (PMID 26569395, 2015).
breast cancer (continued). "Indeed, overexpression of DUSP2 in ErbB2-positve breast cancer cells reverses hypoxia-mediated lapatinib resistance." (PMID 25596742, 2015). "ZNF217 and ErbB3 expression levels showed significant correlation in human breast tumors, and ectopic ZNF217 expression induced ErbB3 protein overexpression in normal human mammary epithelial cells (HMECs) and in breast cancer cell lines (paired with increased ErbB2 expression)." (PMID 26431164, 2015). "Somatic mutations (not including amplifications) in ERBB2 have since been shown to be generally rare in breast cancer but interestingly were significantly enriched in the ILC subtype." (PMID 25849106, 2015). "Indeed, development of targeted therapy against EGFR/ERBB2, such as a lapatinib, have significantly improved treatment of ERBB2-positive breast cancer." (PMID 25596742, 2015). "It is therefore possible that relapses observed in ErbB2-positive breast cancer patients receiving adjuvant Trastuzumab (humanized antibody anti-Her2-Herceptin) or Lapatinib (small tyrosine kinases inhibitor molecule), is due to the presence of CSCs that escape these therapeutic agents." (PMID 26181203, 2015). "Additionally, a co-overexpression of LASP1 with the ERBB2 (Her2/neu) oncogene was reported for human breast cancer tissues, as both genes are in close vicinity on the 17q11-21 region." (PMID 25622104, 2015). "In breast cancer these include, overexpression/amplification of HER2 (ErbB2/neu), activating mutations in PIK3CA, the gene encoding the α catalytic subunit of PI3K, mutation or amplification of AKT and loss of the lipid phosphatase, phosphatase and tensin homolog (PTEN)." (PMID 26095475, 2015). "In addition, we show that targeting the ERK pathway in hypoxic ERBB2-positive breast cancer cells sensitizes to lapatinib treatment." (PMID 25596742, 2015). "Additionally, p66ShcA overexpression promotes EMT in ErbB2-driven breast cancer cells, through up-regulated activation of the c-Met receptor by its ligand hepatocyte growth factor (HGF)." (PMID 26680585, 2015). "Of note, in the course of treatment for this primary breast cancer, the patient did receive anti-ERBB2 therapy as part of her treatment regimen, which a recent study has shown may actually contribute to the development of brain metastases." (PMID 25970776, 2015). "In addition, studies have shown that NF-κB promotes ErbB2-mediated tumorigenesis in vivo by enhancing tumor neo-angiogenesis, and that IKKα plays an important role in providing stimuli that maintain mammary tumor-initiating cells." (PMID 25918934, 2015). "Thus, trastuzumab, pertuzumab, and ado-trastuzumabemtansine, which are given intravenously, are monoclonal antibodies that target the ErbB extracellular domains and are used for the treatment of ErbB2-positive breast cancer." (PMID 26258011, 2015). "Of the 11 ErbB2 SNPs studied that caused HER2-neu protein amino acid variations, only two, corresponding to Ile 655 Val and Pro 1170 Ala, were found to have variation among the ethnically mixed population with HER2 positive breast cancer in this study." (PMID 25885598, 2015). "Moreover, evidence has suggested that a multiepitope derived from an ErbB-2 vaccine suppressed the growth of breast cancer stem cells and consequently prevented tumorigenesis." (PMID 26568964, 2015). "Additionally, p120 was indispensable for the ability of HER2/ErbB2 to promote invasiveness in breast cancer cell lines." (PMID 26067913, 2015). "We examined expression of DUSP2 in ERBB2-positive breast cancer samples using Kaplan-Meier Plotter and found that in 207 ERBB2-positive breast cancer patients with reduced DUSP2 levels showed a decreased trend in relapse-free survival that was not significant (p = 0.15)." (PMID 25596742, 2015). "Finally, the combination of frequencies of copy number changes of two genes was detected in LVI-positive breast cancer group: gains of ERBB2 and losses of RERGL." (PMID 25391423, 2015).
breast cancer (continued). "Including PTK6 inhibitors as part of a treatment regimen could have distinct benefits in ERBB2/HER2-positive breast cancers." (PMID 26247733, 2015). "Since hypoxia is associated with resistance to standard chemotherapy, we examined whether hypoxia alters response of ERBB2-positive breast cancer cells to targeted therapies such as lapatinib." (PMID 25596742, 2015). "Furthermore, PKCδ is required for ErbB2 (HER2)-driven mammary gland tumorigenesis and negatively correlates with prognosis in human breast cancer." (PMID 26633375, 2015). "Indeed, breast cancer is categorized into histopathologic subtypes based on estrogen (ER) and progesterone (PR) hormone receptor status and HER2/ErbB2 epidermal growth factor (EGF) receptors' expression levels." (PMID 26258011, 2015). "Thus, hypoxia blocks lapatinib-mediated cell death in ERBB2-positive breast cancer cells in both standard and in 3D culture conditions." (PMID 25596742, 2015). "Thus, we analyzed RNA-seq data sets from six human tissues (brain, heart, liver, lung, ovary, and testis) and from a ERBB2-positive breast cancer and the control breast tissue (NBS)." (PMID 25934563, 2015). "Moreover, previous studies showed that PYK2 and its closely related kinase FAK are highly expressed in ErbB2-positive breast cancers and contribute to the proliferative and invasive potential of breast cancer cell lines." (PMID 26084289, 2015). "Interestingly, a small region of (focal) copy number gain on chromosome 17 (including the ERBB2 locus) is found in almost half (6/14) of the CHEK2*1100delC breast cancers." (PMID 26553136, 2015). "Finally, EGFR and ErbB2/Her2 signaling triggered by PARs results in prolonged Erk-1/2 activation leading to breast carcinoma cell invasion." (PMID 26573921, 2015). "Furthermore, the development of multifocal, highly metastatic mammary tumors is greatly accelerated in a transgenic mouse model that overexpresses ErbB2 in the same mammary epithelial cells in which PTEN has been deleted." (PMID 25295225, 2014). "ErbB2 is known to be up-regulated during mammary tumour progression in the MMTV-PyV mT model." (PMID 24457046, 2014). "We have recently tested the hypothesis that MM-121 abrogates erbB3 signaling-mediated resistance to trastuzumab and paclitaxel in erbB2+ breast cancer cells via inactivation of erbB3 and its downstream PI-3 K/Akt signaling." (PMID 24886126, 2014). "Also, macroH2A1.2 is by far the predominant form in MCF-7 breast cancer cell line and can interact with HER-2 in the nucleus to enhance the over-expression of oncogene ERBB2." (PMID 25003966, 2014). "ErbB2 overexpression induces expression of cysteine cathepsins B and L leading to their increased activity, which is necessary for ErbB2-induced invasion of ErbB2 and p95 ErbB2 expressing breast cancer cells." (PMID 24709902, 2014). "In vitro, studies revealed that fascin exhibits highly increased levels in breast cancer cell lines over-expressing the receptor tyrosine kinase and prognostic indicator c-erbB-2/HER-2, and that such cells exhibit dramatically increased cell dynamics and in vitro motility." (PMID 24993803, 2014). "We explored the initial phase of ErbB2+ mammary cancer progression in mice focusing on two aspects." (PMID 25184361, 2014). "In order to investigate the role of the conserved acetylation sites of Pparγ in lipogenesis, ErbB2 overexpressing breast cancer cells were used and lysyl residues were substituted with alanine (K to A) or glutamine (K to Q) to generate residues that were incapable of being acetylated." (PMID 25229978, 2014). "Patients with tumors of the luminal-like subtype are predicted to have a better prognosis than those who experienced basal-like breast cancer, a similar prognosis to those with ERBB2+, luminal B, or claudin-low tumors, but a worse prognosis than patients with luminal A and normal-like breast tumors." (PMID 25076125, 2014).